PPARA (peroxisome proliferator activated receptor alpha)
Diseases named in the same sentence as PPARA in open-access papers (continued):
Sharing a sentence is not in itself a finding about the gene and the disease.
steatosis (continued). "As we saw earlier when we looked at the relationship between PPARs and liver disease, the application of CBD restored the protein expression of hepatic PPARα in a chronic alcohol-fed mouse model, improving alcohol-induced hepatic metabolic imbalance and steatosis." (PMID 38397045, 2024). "Interestingly, in the mice lacking cytochrome P450 2A5 (CYP2A5), i.e., cyp2a5−/− mice, we observed an elevated basal level of PPARα, but more severe ethanol-induced steatosis." (PMID 38790950, 2024). "Thus, N800 treatment suppresses the expressions of transcription factors, including Foxa1, Srebp1c, and Pparα, and then induces hepatic MS, in line with the other types of drug-induced steatosis." (PMID 39061900, 2024). "By contrast, we found microvesicular steatosis in the SIV-infected macaques, a condition associated with mitochondrial dysfunction and impairment of the beta-oxidation of fatty acids concurrent with increased PPARA expression." (PMID 38400071, 2024). "MPEP administration is able to almost double the expression of PPARα in our model of steatosis, and the increase in the mRNA expression of its target gene Acox1 confirm our hypothesis." (PMID 37047048, 2023). "Disruption of hepatic PPARα signaling induces severe steatosis after acute fasting." (PMID 37503004, 2023). "Moreover, treatment with a PPARα agonist (Wy14,643) restored the activation of PPARα and target gene expression, thereby increasing FA β-oxidation in alcohol fed mice and preventing steatosis formation." (PMID 35864895, 2022). "PPARα has been shown to enhance free fatty acid β-oxidation and blunt the development of steatosis." (PMID 35990329, 2022). "The mechanism involved in the onset of tetracycline-induced steatosis involves the inhibition of fatty acid oxidation genes, such as PPARα, CPT1 and fatty acid binding protein 1, and the decrease in hepatic lipoprotein secretion via microsomal triglyceride transfer protein inhibition." (PMID 35052872, 2022). "PPARα knockout mice given a high-fat diet were found to have severe steatosis and hepatitis." (PMID 35050176, 2022). "This suggests simultaneous activation of lipogenesis and lipolysis in the steatotic liver and indicates a protective PPARα function, supported by PPARα KO studies showing the exacerbation of NAFLD progression and fenofibrate (PPARα agonist) studies showing reduced steatosis." (PMID 35269495, 2022). "PPARα activity for using fatty acid is important to block steatosis during fasting in mice." (PMID 35035496, 2022). "We found that SZ-A inhibited CD36 and PPARγ mRNA expression and promoted PPARα mRNA expression, suggesting that SZ-A may decrease hepatic lipid accumulation and steatosis by inhibiting de novo lipogenesis and fatty acid uptake, while promoting β-oxidation." (PMID 35624769, 2022). "So, replenishing choline deficiency in the fatty liver with EPLs may stimulate endogenous ligand synthesis to activate PPARα and, therefore, beta-oxidation of fatty acids in the liver leading to steatosis regression." (PMID 35359878, 2022). "PPARα downregulation could also be linked to the advanced glycation end product receptor (RAGE) in older mice, and its downregulation improved PPARα, mitochondrial β-oxidation and steatosis." (PMID 35855331, 2022). "Pparα is the transcription factor regulating lipid metabolism and could activate Cpt1 to improve steatosis induced by excess lipid deposition." (PMID 36421446, 2022). "Acetaldehyde, a metabolite of ethanol, can directly inhibit PPARa activity to promote steatosis." (PMID 34819599, 2021). "Several studies have found that inhibiting miR-21 could alleviate steatosis through activating PPARα 16, 17; however, the role of miR-21 in targeting PPARα requires further investigation." (PMID 33994867, 2021). "PPARα agonist treatment reversed the effects of hypoxia on steatosis." (PMID 34692739, 2021).
steatosis (continued). "Furthermore, hepatic PPARα can protect the liver against fasting/high-fat diet-induced steatosis, by transactivating the genes required for fatty acid catabolism and repressing several inflammatory genes." (PMID 34445672, 2021). "We observed that Pparαhep−/− and Pparα−/− mice developed steatosis upon CTRL diet feeding." (PMID 32300166, 2020). "In addition to beneficial effects on steatosis and inflammation, PPARα agonist treatment also reverses fibrosis by targeting PPARα in HSC, which decreases the expression of fibrogenic factors including Col1α1 and TIMPs and reduces the number of activated HSC." (PMID 32660130, 2020). "In this study, OA- and cholesterol-induced steatosis led to a decrease in PPARα expression in HepG2 cells, suggesting that this receptor may play a pathogenic role in NAFLD." (PMID 33281535, 2020). "Therefore, when hepatic PPARα is disrupted, extrahepatic PPARα activity compensates to increase and utilize excess lipid, thus protecting livers against fasting-induced steatosis." (PMID 32192216, 2020). "Therefore, hepatocyte-specific Pparα deletion promotes steatosis and liver inflammation while dissociating steatosis from glucose intolerance as observed in Pparα−/− mice." (PMID 32300166, 2020). "miR-21-dependent PPARα downregulation could affect fatty acid oxidation and trigger steatosis in hepatocytes as well as mediate kidney injury and fibrosis in epithelial cells." (PMID 33329700, 2020). "PPARα can improve steatosis and suppress the development of NAFLD." (PMID 32655764, 2020). "Therefore, NAFLD-induced increases in PPARα abundance can be further enhanced by its pharmacological activation: the PPARα agonist WY-14643 protects mice against steatosis and steatohepatitis by preventing intrahepatic lipid and lipoperoxide accumulation." (PMID 32660130, 2020). "However, PPARα was downregulated in patients with NASH compared to both patients with steatosis and healthy controls, and the expression of PPARα decreases with increasing NAFLD activity score and progression of fibrosis." (PMID 31771244, 2019). "Hepatocyte-restricted PPARα deletion can induce steatosis in hepatocyte-specific PPARα-null mice." (PMID 31336903, 2019). "Similarly, expression of Plin5, which also promotes hepatic fat storage, is lower in PPARα−/− mice, despite these mice showing more pronounced steatosis." (PMID 30866796, 2019). "In addition, miR-21 directly targets PPARα and plays a role in development of steatosis by inhibition of PPARα-mediated FA uptake and lipid oxidation." (PMID 31207892, 2019). "However, PPARα was downregulated in patients with NASH compared to patients with steatosis and healthy controls, and the expression of PPARα decreased with increasing NAFLD activity score and fibrosis stage." (PMID 29936596, 2018). "The fact that PPARα-deficient mice develop steatosis rather than steatohepatitis with MDBs33,34 suggests that the appearance of the typical steatohepatitis phenotype requires an additional “hit” that most likely targets the suppressed stress response." (PMID 30154499, 2018). "Taken together, these results suggest that MG exerts protective effects against steatosis, hyperlipidemia, and the underlying mechanism, which may be closely associated with AKT/AMPK/PPARα activation and MAPK/NF-κB/SREBP-1c inhibition." (PMID 29467759, 2018). "Therefore, we generated a hepatocyte-specific Pparα-null mouse and found that hepatocyte-restricted Pparα deletion is sufficient to promote steatosis." (PMID 29954129, 2018). "PPARα restoration led to the transcriptional activation of genes associated with lipid metabolism, including carnitine palmitoyltransferase 2 (CPT2) and acyl-CoA binding domain containing 3 (ACBD3), and then resulted in the steatosis resolution." (PMID 29018509, 2017).
steatosis (continued). "Dramatically, PPARα repression indeed occurred in the steatosis group with statistical significance at both transcriptional and translational levels, indicating an impact on the circRNA_0046367/miR-34a/PPARα regulatory system with steatosis-inducing characteristics." (PMID 29018509, 2017). "However, PPARα is absolutely required for the metabolic adaptation to fasting, since PPARα−/− mice, either full body or liver-specific, develop steatosis with prolonged fasting." (PMID 28115925, 2016). "PPARα activity is regulated by fatty acids and protects from steatosis, suggesting that dietary essential fatty acids may control the activity of this nuclear receptor." (PMID 27669233, 2016). "In the long term, PPARα deficiency leads to spontaneous steatosis in both fed and fasted mice, regardless of the dietary fat consumed." (PMID 27669233, 2016). "Meanwhile it has been shown that, in healthy individuals, peroxisome proliferator-activated receptor alpha (PPAR-α) acts to ameliorate steatosis but, in the presence of mitochondria dysfunction—which can be seen in HCV patients—PPAR-α may exacerbate steatosis." (PMID 26276502, 2016). "Thus, an AOP leading to steatosis and steatohepatitis involves suppression of PPARα activity and accumulation of fats due to decreases in fatty acid catabolism." (PMID 25689681, 2015). "Our screen identified chemicals, diets and infections that activate or suppress PPARα and could potentially contribute to liver cancer or steatosis, respectively." (PMID 25689681, 2015). "Furthermore, in the HepG2 cells treated with aliskiren, we found that aliskiren decreased intracellular steatosis at a higher dose with up-regulation of PPARα, which was similar to the findings in our MCD-Ali group." (PMID 24204981, 2013). "However, there is concurrent increase in PPARα and PPARδ levels which would be expected to result in enhanced oxidation of lipids and resolution of steatosis." (PMID 23483972, 2013). "The forced increase in NEFA level from adipocytes due to FGFR1 deficit under prolonged starvation, likely in part resulted in the observed compensatory increases of hepatic and serum FGF21 through hepatic PPARα, and the elevated hepatic lipogenesis and steatosis as well." (PMID 23106963, 2012). "Indeed, PPARα expression is decreased in the liver of rodents with NAFLD and PPARα knockout mice display an increased steatosis, oxidative stress, and inflammation when fed an HF Western diet." (PMID 23024649, 2012). "Numerous studies suggest that the actions of PPARα can prevent steatosis." (PMID 22675337, 2012). "An aberrant expression of PPARα also contributes to the hepatocarcinogenic events induced by the solvent trichloroethylene (TCE) in rodents and PPARα activation was necessary to induce steatosis and HCC in a model of transgenic mice expressing the HCV core protein." (PMID 23024649, 2012). "Persistent activation of PPARα ameliorates hepatic steatosis and inflammation in mice but may also induce hepatocarcinogenesis." (PMID 22645601, 2012). "Furthermore, treatment with a PPARα agonist improved steatosis in fatty liver Shionogi mice and reduced hepatic triglyceride level by inducing expression of several genes involved in the turnover of fatty acids, e.g., ACADL." (PMID 21339799, 2011). "Inhibition of PPARα signaling may impair lipoprotein transport, reduce fatty acid oxidation and enhance lipogenesis, which ultimately induces the development of steatosis." (PMID 21087523, 2010). "The inhibitory effect of PPARα on progression of steatosis to steatohepatitis may be mediated in part by COX2 (Ptgs2), a candidate gene involved in steatohepatitis development that is suppressed by PPARα." (PMID 20936127, 2010).
steatosis (continued). "Notably, PPARα deletion has been reported to promote steatosis and liver inflammation." (PMID 40806595, 2025). "Accompanying the steatosis during acute infection, we detected changes in the liver in the expression of genes involved in metabolism, particularly the peroxisome proliferator-activated receptor alpha (PPARalpha), which is involved in beta-oxidation and cholesterol metabolism." (PMID 38400071, 2024). "Moreover, activation of PPARα ameliorates liver fibrosis and inhibits the function of hepatocyte-specific G-protein pathway suppressor 2 (GPS2), alleviating the development of diet-induced steatosis and fibrosis and causing activation of lipid catabolic genes." (PMID 38004166, 2023). "In addition, hepatic RNA sequencing from obese individuals with steatosis revealed lower expression of PPARα, carnitine palmitoyl transferase 1 (CPT1), and also the gene encoding hydroxy-methylglutaryl-CoA synthase 2 (HMGCS2), the rate-limiting enzyme in ketogenesis." (PMID 37591342, 2023). "However, fasted Hmgcs2ΔLiv mice showed a similar increase in the FAO genes, suggesting that steatosis in Hmgcs2ΔLiv mice is not caused by impaired PPARα signaling." (PMID 37503004, 2023). "Further research indicated that inhibition of miR-21 could alleviate steatosis by activating PPARα." (PMID 37190114, 2023). "It remains unknown whether the increased steatosis susceptibility in mice lacking PPARα depends on PPARα activity only in hepatocytes or also in other organs." (PMID 35625520, 2022). "In addition to steatosis, PPARα activation might also protect against other liver lesions induced by PFOA, such as bile duct hyperplasia and hematopoietic cell proliferation." (PMID 35162986, 2022). "In addition, OA-induced steatosis causes changes in cell morphology; increases tumor necrosis factor alpha (TNF-α) levels, lipid peroxidation, and apoptosis; and decreases expression of peroxisome proliferator-activated receptor alpha (PPAR-α)." (PMID 36012291, 2022). "Similarly, downregulated PPARα responsive genes have also been reported in alcohol fed rats, which corresponded to increased steatosis and liver injury, and that PPARα activation with Clofibrate restores the expression of PPARα regulated genes, and reduces steatosis severity and markers of ALD." (PMID 35864895, 2022). "As documented by our results, the dual activation of PPARα/γ by saroglitazar could effectively improve steatosis, fibrosis, and aspects of necro-inflammation in the HF-induced NASH model more than fenofibrate and pioglitazone, and it can be more beneficial in the management of NASH." (PMID 34593018, 2021). "In short, we conclude that PPARα functions both as a prenatally anticipatory and postnatally adaptive regulator of lipid catabolism, ultimately protecting the postnatal liver against a rapid insurgence of steatosis by promoting the use of milk lipids as an energy source." (PMID 27367842, 2016). "Moreover, pioglitazone also binds and activates PPARα with low potency, which could explain its better performance than rosiglitazone in ameliorating steatosis." (PMID 28115925, 2016). "Therefore, plasma vanin activity could possibly serve as a valuable marker of hepatic PPARα activation and/or steatosis in obese subjects." (PMID 26932716, 2016). "However, fasting-induced steatosis was more severe in Pparα−/− mice than in wild-type mice." (PMID 27669233, 2016). "Future studies could focus on the quantitative relationships between level of PPARα suppression and hypothesized phenotypic consequences of suppression of fatty acid catabolism and transport that can lead to steatosis and under prolonged exposure conditions, steatohepatitus." (PMID 25689681, 2015). "However, macrovesicular steatosis was more common in hPPARα mice than in Pparα-null mice." (PMID 20709644, 2010). "As expected, the PPARA function was augmented in AEG-1-L24K/L25H mice, which provided partial protection from HFD-induced steatosis." (PMID 40282551, 2025).
steatosis (continued). "In the liver, a lack of curcumin results in increased SREBP1c-driven lipogenesis and suppressed β-oxidation via PPARα activation, along with aggravated NF-κB/TGF-β signaling and reduced insulin sensitivity, leading to steatosis and fibrosis." (PMID 41471280, 2025). "The liver is the predominant site of PPARα activity and is the primary target of AFB1-generated NAFLD damage, which drives steatosis, cholestasis, and carcinogenic changes." (PMID 40793786, 2025). "Histology confirmed reduced steatosis, while Western blotting showed downregulation of SREBP-1, HMGCR, and ACC, and upregulation of CPT-1, PPARα, and phosphorylated AMPK." (PMID 40943363, 2025). "We also find that ZFD induces steatosis in GF mice, possibly due to low PUFA levels, which can increase SREBP-1c activity and decrease PPARα activity, leading to increased expression of lipogenic genes like Elovl6 and Scd1 and a shift toward lipid synthesis." (PMID 40345386, 2025). "Autophagy deficiency disrupts this intricate balance, leading to impaired activity of PPARα and FXR, metabolic dysfunction, and liver pathologies, such as steatosis and cholestasis." (PMID 40565288, 2025). "Our results suggest GPS’s anti-inflammatory and anti-steatosis effects in NASH progression are related to the suppression of HIF-1α through the restoration of L-serine and glycine and the activation of PPARα through increased EPA and DHA." (PMID 38515850, 2024). "In this context, the upregulation of miR-34a results in the downregulation of hepatic PPARα and SIRT1, which results in reduced fatty acid oxidation and the development of steatosis." (PMID 39133714, 2024). "As previously observed, p-AMPK, PGC-1α, and PPARα were downregulated in HFD-induced liver injury and FFA-induced hepatocyte steatosis." (PMID 38532480, 2024). "The data in the present study showed that expression of Pparα mRNA was elevated by the LAB bacteria in the order HY7804 > LP158 > LPC226, a pattern similar to the degree of decrease in steatosis grade." (PMID 37894124, 2023). "Downregulation of miR-483-5p links HCC, NAFLD, and AFLD, inducing the upregulation of PPARα and TIMP2 responsible for the increased steatosis and fibrosis and HCC progression as well (brown arrow)." (PMID 37958352, 2023). "Significant reductions in the levels of PPARα and CPT1/2 have been documented in the livers of HFD-fed animals and are considered a major mechanism for the development of steatosis." (PMID 38004149, 2023). "Mechanistically, miR-483-5p targets Peroxisome-proliferator-activated receptor alpha (PPARα) and Tissue inhibitor of metalloproteinases 2 (TIMP2) gene expression leading to the suppression of steatosis and fibrosis." (PMID 37958352, 2023). "Consistent with impaired hepatic fatty acid oxidation in non-alcoholic steatohepatitis (NASH), mRNA expression of PPARA is decreased in liver biopsies obtained from patients with NASH and inversely correlates with the severity of steatosis." (PMID 35419389, 2022). "Numerous studies have been designed to activate PPARA for slowing the progression or curing NAFLD, and they demonstrate enhancement in metabolic activity and decrease of steatosis and fibrosis in NAFLD patients and models." (PMID 35405942, 2022). "Taken together, our results suggest that ATL I acts as a promising compound that activates SIRT6/PPARα signaling and attenuates the NLRP3 inflammasome to ameliorate hepatic inflammation and steatosis." (PMID 36558977, 2022). "Liver PPARα expression was negatively correlated with the presence of NASH and with the severity of steatosis, hepatocytes ballooning, the NASH activity score and fibrosis." (PMID 35625520, 2022). "Dual activation of PPARγ and PPARα has a favourable effect in ameliorating NASH by reducing inflammation, steatosis, and fibrosis." (PMID 35773269, 2022).